MPO (myeloperoxidase)
Diseases named in the same sentence as MPO in open-access papers (continued):
Sharing a sentence is not in itself a finding about the gene and the disease.
oral lichen planus (1 paper, 2025). Oral lichen planus is a chronic inflammatory oral condition of unknown aetiology characterized by T-cell-mediated chronic immune response and abnormal epithelial keratinization cycle. "Previous studies have shown that TGF-β stimulation increases NET formation in neutrophils from patients with oral lichen planus, characterized by elevated levels of myeloperoxidase, citrullinated histone H3, and cell-free DNA." (PMID 40338657, 2025).
orbital pseudotumor (1 paper, 2013). "After remission by steroid treatment, our patient relapsed and presented with an orbital pseudotumor without re-elevation of MPO-ANCA." (PMID 23617946, 2013).
otitis (1 paper, 2021). "Myeloperoxidase is associated with neutrophil release and is known to reduce Spn burdens at the expensive of tissue damage during otitis." (PMID 33705390, 2021).
otitis media with effusion (1 paper, 2024). Otitis media associated with accumulation of fluid in the middle ear. "Previous studies have evaluated ROS and free radicals associated with otitis media with effusion (OME), including O2·−, H2O2, ·OH, lipid hydroperoxide, myeloperoxidase, nitric oxide, xanthine oxidase, and malondialdehyde." (PMID 39857337, 2024).
papillary thyroid carcinoma (1 paper, 2021). "In the pathological evaluation, CD34-, CD117-, MPO-, and HLA-DR-positive blastic cells which infiltrated into follicular variant papillary thyroid carcinoma were detected." (PMID 34325712, 2021).
papilloma (1 paper, 2022). A benign epithelial neoplasm that projects above the surrounding epithelial surface and consists of villous or arborescent outgrowths of fibrovascular stroma. "Papillomas also showed infiltration of immune cells, such as macrophages (F4/80), neutrophils (MPO), T cells (CD3), and B cells (CD45R)." (PMID 36261000, 2022).
pelvic inflammatory disease (1 paper, 2019). Pelvic inflammatory disease (PID) is an acute or chronic inflammation in the pelvic cavity. "Systemic levels of MPO are elevated, e.g., in patients with pelvic inflammatory disease and rheumatic arthritis." (PMID 31236065, 2019).
pneumonitis (1 paper, 2020). An inflammatory process affecting the lung parenchyma. "Both myeloperoxidase (MPO) and matrix metallopeptidase-9 (MMP-9), products of activated neutrophils, and lactate dehydrogenase (LDH), a surrogate marker of tissue injury, were markedly increased in the BAL fluid of patients with pneumonitis." (PMID 33584685, 2020).
Protein-losing enteropathy (1 paper, 2021). Abnormal loss of protein from the digestive tract related to excessive leakage of plasma proteins into the lumen of the gastrointestinal tract. "Whereas α1-antitrypsin (α1AT; a marker of protein-losing enteropathy) was highest in Malawi and lowest in the UK, both myeloperoxidase (MPO; a marker of neutrophil activity) and α1 acid glycoprotein (a marker of systemic inflammation) were highest in Indian infants." (PMID 34911947, 2021).
protozoal infections (1 paper, 2022). "sCD40L was strongly inversely associated with IL-8, proline, MPO, and protozoal infections." (PMID 36096405, 2022). "In particular, markers of intestinal permeability and inflammation measured in urine (lactulose, mannitol) and stool (MPO, protozoal infections) during infancy may predict disruptions to cytokine and adipocytokine production in later childhood that are precursors to MetS in adulthood." (PMID 36096405, 2022).
Pseudomonas infection (1 paper, 2022). Infections with bacteria of the genus pseudomonas. "Likewise, neutrophil activation, determined by quantification of cell surface CD11b expression and by measuring the neutrophil degranulation products MPO and elastase in BALF was comparable in Dnmt3bfl/flMrp8Cre and control mice at both time points after Pseudomonas infection." (PMID 35269409, 2022).
psychotic disorder (1 paper, 2020). An abnormal condition of the mind that involves a loss of contact with reality. "Plasma levels of high-sensitivity C-reactive protein (hs-CRP) and myeloperoxidase (MPO) were higher (p<0.05, p<0.001) in patients with psychotic disorders than in HC, and hs-CRP and MPO were independently associated with atherogenic lipid ratios in the multivariable analyses." (PMID 32754070, 2020). "Patients with psychotic disorders have a markedly higher CVD risk compared to healthy controls as reflected by atherogenic lipid ratios, and the increased risk is associated with elevated hs-CRP and MPO reflecting subclinical inflammation and abnormal neutrophil activation in such patients." (PMID 32754070, 2020). "Furthermore, elevated neutrophil counts have been reported in BD and SCZ and based on the increased MPO levels observed in our study, it is tempting to speculate that abnormalities in neutrophil activation could represent an early event in the progression of CVD in patients with psychotic disorders." (PMID 32754070, 2020).
pulpitis (1 paper, 2024). Inflammation of the dental pulp. "In the dog model of experimental pulpitis, luteolin treatment suppressed the expression of pPKR-, MPO-, and CD68-positive cells in pulp tissues, whereas guaiacol-parachlorophenol treatment caused coagulative necrosis and disruption." (PMID 38304347, 2024).
radiation pneumonitis (1 paper, 2024). Inflammation of the lung due to harmful effects of ionizing or non-ionizing radiation. "Moreover, we investigated oxidative status during radiation pneumonitis by examining MPO, MDA, SOD, GSH, and LDH levels in RP mice serum." (PMID 38790718, 2024).
renovascular hypertension (1 paper, 2021). High blood pressure secondary to renal artery stenosis. "The presence of renovascular hypertension was also associated with oxidative stress markers, such as increased MPO activity and reduced GSH concentrations in the duodenum." (PMID 34777003, 2021).
salmonellosis (1 paper, 2020). Infections with bacteria of the genus salmonella. "The higher upregulation of pro-inflammatory genes (Ifnγ, Kc, Inos, Il1β) and the higher concentration of immune proteins (MPO, KC) that we observed in SA+/ST−/mCRAMP−/− and SA+/ST+/mCRAMP−/− mice are clear indications of a higher susceptibility to salmonellosis when cathelicidin is absent." (PMID 33292444, 2020).
SAPHO syndrome (1 paper, 2025). SAPHO syndrome (acronym for Synovitis, Acne, Pustulosis, Hyperostosis and Osteitis) is an auto-inflammatory disease, mainly characterized by the association of neutrophilic cutaneous involvement and chronic osteomyelitis. "This case highlights the first reported occurrence of SAPHO syndrome associated with MPO-ANCA positivity and underscores the need for further research to explore the relationship between autoimmune markers like MPO-ANCA and SAPHO syndrome." (PMID 40497194, 2025).
Senile plaques (1 paper, 2020). Senile plaques are extracellular deposits of amyloid in the gray matter of the brain. "In AD, elevated MPO levels have been reported to be localized in senile plaques and some activated microglia of the frontal cortex." (PMID 32842621, 2020).
serous ovarian carcinomas (1 paper, 2016). "Biopsies of mostly high-grade primary serous ovarian carcinomas and their matched recurrences were stained with MPO after fixation in formalin and embedding in paraffin." (PMID 27531373, 2016).
skin infection (1 paper, 2012). An inflammatory process affecting the skin, caused by bacteria, viruses, parasites, or fungi. "Next, we used the myeloperoxidase assay to quantify neutrophil ingress to the skin infection sites of MGAS5005 and ΔsseMGAS5005 at 24 h after subcutaneous infection of BALB/c mice." (PMID 22496650, 2012).
sphenoidal sinusitis (1 paper, 2025). "Further testing also revealed a positive perinuclear antineutrophil cytoplasmic antibodies (p-ANCA), also known as myeloperoxidase (MPO)-ANCA, and a CT scan of the sinuses showed acute-on-chronic left sphenoidal sinusitis." (PMID 40406763, 2025).
streptococcal infection (1 paper, 2013). Any of the several infectious disorders caused by members of streptococcus, a genus of gram positive bacteria belonging to the family Streptococcaceae. "In the present study, it was observed that NSC23766 reduced M1 protein-induced pulmonary MPO activity by 48%, suggesting that Rac1 activity plays a significant role in neutrophil infiltration in streptococcal infections." (PMID 23951087, 2013).
systemic fungal infection (1 paper, 2022). "However, rare episodes of severe systemic fungal infection have also been reported in patients with complete MPO deficiency, suggesting that MPO might play more essential roles in systemic immunity." (PMID 35945238, 2022).
Tetralogy of Fallot (1 paper, 2022). A congenital cardiac malformation comprising pulmonary stenosis, overriding aorta, ventricular septum defect, and right ventricular hypertrophy. "In fact, preoperatively, surfactant-specific protein SP-B is increased in all CHD, while MPO (neutrophil) activity is decreased only in tetralogy of Fallot, and albumin and surfactant-specific protein-A are increased only in ASD and ventricular septal defect, compared to age-matched controls." (PMID 35333340, 2022).
thoracic cancer (1 paper, 2023). A primary or metastatic malignant neoplasm affecting the tissues of the thorax. "To date, strong links between MPO and radiation injury to the heart in patients with thoracic cancers have not been established but the clinical utility of MPO is of continued investigative interest." (PMID 37796395, 2023).
trichomoniasis (1 paper, 2011). An infection that is caused by Trichomonas. "For exampleMIP-1α, VEGF and MPO levels were significantly different than controls inChlamydia and trichomoniasis but not BV while in contrast,IL-6, IL-10, GM-CSF, G-CSF, IL-3, IL-7 and IL-12 were significantly changed inChlamydia and BV but not trichomoniasis." (PMID 21572958, 2011).
Ureaplasma infection (1 paper, 2020). "Our result showed increased intestinal MPO, CD4, and TLRs in response to such prenatal inflammation, which are similar to those that resulted from Ureaplasma infection in sheep model, suggesting common underlying mechanisms." (PMID 32265914, 2020).
vaginal infections (1 paper, 2025). "The UDN patient with compound heterozygous variants in the MPO gene is highly sensitive to recurrent infections—including yeast infections and recurrent vaginal infections." (PMID 39825393, 2025).
vascular ED (1 paper, 2021). "Myeloperoxidase (MPO)-dependent ox-LDL (Mox-LDL) was detected in penile tissues in patients with vascular ED, but not in those with prostatectomy-caused neurogenic ED." (PMID 34829887, 2021).
Ventricular arrhythmia (1 paper, 2024). "Consistent with this, increased plasma MPO in MI patients undergoing primary PCI independently predicts increased in-hospital mortality and subsequent clinical complications, including ventricular arrhythmia, which is the leading acute cause of death post-MI." (PMID 39061857, 2024). "Notably, MPO gene-deficient mice showed a reduced slowdown and heterogeneity of electrical conduction in the peri-infarct zone relative to wild-type mice 21 days post-MI, which supports a role for MPO as a mediator of ventricular arrhythmias." (PMID 39061857, 2024). "MI patients with arrhythmic events including ventricular arrhythmia, sudden cardiac death, or cardioverter-defibrillator implantation, have significantly higher circulating MPO levels than those without arrhythmic events." (PMID 39061857, 2024).
ventricular fibrillation (1 paper, 2019). A disorder characterized by an electrocardiographic finding of a rapid grossly irregular ventricular rhythm with marked variability in QRS cycle length, morphology, and amplitude. "Hence, experimental MPO deficiency models were created in mice and linked to significantly smaller left ventricle dilatation, leading to improved ventricular function and smaller collagen deposition together with decreased susceptibility to both atrial and ventricular fibrillation." (PMID 31416120, 2019).
Vocal cord paralysis (1 paper, 2017). A loss of the ability to move the vocal folds. "After careful search of potential conditions that could have explained her main symptoms, and in the absence of systemic involvement, the patient was labeled as having an "MPO-ANCA positive isolated vocal cord paralysis" and was sent to vocal rehabilitation with regular follow-up." (PMID 28559644, 2017).
xerostomia (1 paper, 2022). Dryness of the mouth resulting from reduced salivary secretion. "Other genes that may be of interest in the development and treatment of xerostomia are MPO and TNFSF13B, both of which are involved in the significantly overrepresented GO ‘immune system process’ (GO:002376)." (PMID 35268532, 2022). "The PPI network genes IL6R, EGFR, NFKB1, MPO, and TNFSF13B constitute a possible biomarker signature of xerostomia." (PMID 35268532, 2022). "The IL6R, EGFR, NFKB1, MPO, and TNFSF13B genes might all have implications in the diagnosis and intervention of xerostomia." (PMID 35268532, 2022).
infection (485 papers, 2006 to 2026). The state of being infected such as from the introduction of a foreign agent such as serum, vaccine, antigenic substance or organism. "The infection with atypical EPEC had significant positive association with levels of Myeloperoxidase (b = 0.38; 95% CI = 0.11, 0.65; p-value = 0.006)." (PMID 40276386, 2025). "This study aimed to identify the factors associated with early infection following remission induction therapy in older adults with MPO-AAV." (PMID 41408511, 2025). "This study aimed to explore risk factors for early infection after therapy initiation in older adults with MPO-AAV." (PMID 41408511, 2025). "This causes asthenozoospermia with a high DFI; low-grade infections and leukocytospermia inject proteases and MPO-derived oxidants, which break apart tetraspanin partners and oxidise head rafts." (PMID 41465073, 2025). "We aimed to identify the risk factors for early-phase infection during treatment initiation in older adults (aged ≥ 75 years) with myeloperoxidase (MPO)-ANCA-positive AAV (MPO-AAV)." (PMID 41408511, 2025). "NETs are a natural defense barrier composed of MPO, neutrophil elastase and histones, and NETs are formed by neutrophils after stimulation with pathogenic infections." (PMID 40138332, 2025). "Population studies utilizing Bayer-Technicon hematological devices have found that a small number of patients with complete MPO deficiency experience severe complications related to infection or inflammation pathologies." (PMID 38275657, 2024). "This view is however challenged by a study of 100 individuals with partial or total MPO deficiency that indicates a protective effect against cardiovascular damage, but also increased incidence of severe infections and chronic inflammatory conditions." (PMID 37954595, 2023). "The elevated levels of MPO seen directly correspond to the observed increases in neutrophils in severe infection, and MPO production by neutrophils has been associated with COVID-19 disease pathology." (PMID 37598150, 2023). "The increase in chemokine expression was most apparent in MPO-deficient mice compared to the WT mice after infection." (PMID 38037141, 2023). "The disparity in the clinical manifestations of CGD, where patients suffer significant infection‐related morbidity and mortality, and MPO deficiency, which somewhat surprisingly goes largely unnoticed, questions the predominance of a single killing mechanism." (PMID 36440666, 2023). "In this study, we reported that influenza virus infection increases a host’s susceptibility to secondary infection by P. aeruginosa by reducing the MPO activity of neutrophils." (PMID 36475755, 2023). "At 12 h post-infection, WT mice carried a low kidney fungal load, whereas MPO-deficient and Clo-L-treated mice exhibited comparably elevated fungal loads." (PMID 35945238, 2022). "WT mice infected with 1 × 105 WT C. albicans succumbed 7–15 days post-infection, whereas MPO-deficient animals developed severe symptoms within 12 h post-infection, exhibiting a substantial decrease in body temperature." (PMID 35945238, 2022). "While severe MPO deficiency is associated with an increased risk for infection, the incidence of cardiovascular diseases appears to be lower in MPO-deficient individuals as compared to the reference population." (PMID 36421487, 2022). "Individuals with MPO deficiency are less efficient to kill intracellular pathogens and also experience higher rates of infections and chronic inflammatory conditions." (PMID 36510129, 2022). "In this scenario SIGNR1 and MPO play competing roles, with MPO being critical to protect the spleen from infection and SIGNR1-mediated capture eliciting a pathogenic programme that undermines MPO effector mechanisms." (PMID 35945238, 2022). "To investigate which organs were afflicted by the MPO deficiency we examined the fungal load at 12 h post-infection." (PMID 35945238, 2022).